AVP (arginine vasopressin)
Diseases named in the same sentence as AVP in open-access papers (continued):
Sharing a sentence is not in itself a finding about the gene and the disease.
endolymphatic hydrops (7 papers, 2011 to 2025). An accumulation of endolymph in the inner ear (labyrinth) leading to buildup of pressure and distortion of intralabyrinthine structures, such as cochlea and semicircular canals. "Mechanistic studies on MD predominantly rely on the guinea pig model of endolymphatic hydrops, which can be reliably induced by arginine vasopressin (AVP) or its analog dDAVP." (PMID 41011137, 2025). "It was found that in the guinea pig model of AVP-induced endolymphatic hydrops, plasma AVP concentration was increased, cochlear V2R expression was downregulated, and cyclic adenosine monophosphate (cAMP) and aquaporin 2(AQP2) expression were upregulated." (PMID 39722819, 2024). "Takeda9 established a model of endolymphatic hydrops by injecting arginine vasopressin into the abdomen of guinea pigs." (PMID 37116375, 2023). "Clinically, patients with endolymphatic hydrops (Ménière's disease and delayed endolymphatic hydrops) presented with vertigo, and for those who present with motion sickness, the level of blood AVP was elevated." (PMID 36090271, 2022). "In basic studies there are no reports of endolymphatic hydrops or collapses in the inner ear of AVP- or V2R-deficient mice." (PMID 34659087, 2021). "Moxibustion at Tinggong (SI19) has been demonstrated to down-regulate plasma AVP, cochlear AQP2, and aquaporin 7(AQP7) expression in the animal model with endolymphatic hydrops, thereby achieving the effect of intervening in endolymphatic hydrops." (PMID 39722819, 2024).
hemorrhage (7 papers, 2018 to 2025). Loss of blood from the vascular compartment to the exterior or into nonvascular body space as a result of rupture or severance of the blood vessels. "Thus, in a moderate blood loss the blockade of AT1 receptors with losartan reduces AVP secretion, but in severe blood loss other additional mechanisms probably sustain AVP-secretion in response to hemorrhage after the blockade of AT1 signaling." (PMID 35137852, 2022). "Conversely, icv administration of both NBQX and losartan significantly decreased plasma AVP levels after hemorrhage." (PMID 35137852, 2022). "Next, we used the NBQX, an AMPA receptor antagonist, to evaluate the participation of these receptors in AVP secretion after hemorrhage." (PMID 35137852, 2022). "Thus, the present study aimed to evaluate the participation of L-glutamate AMPA and NMDA receptors and ANG II AT1 receptors in the brain on hemorrhage-induced AVP secretion." (PMID 35137852, 2022). "With hemorrhage, the HPA axis undergoes significant changes in the secretion of adrenocorticotropic hormone (ACTH) and arginine vasopressin (AvP), also known as antidiuretic hormone (ADH)." (PMID 40142918, 2025). "The participation of different ionotropic L-glutamate receptors in hemorrhage-induced AVP release is not known." (PMID 35137852, 2022). "In addition to the participation of different L-glutamate receptors in the control of AVP secretion, in this study we showed that AMPA receptors were involved in the control of AVP release after hemorrhage." (PMID 35137852, 2022). "The icv injection of AP5 did not change AVP secretion in response to hemorrhage." (PMID 35137852, 2022). "In other non-reflex hypotensive circumstances (e.g., severe hemorrhage) in which a central venous pressure fall cannot be readily reversed by AVP, the net action of an increased AVP level may be of compensatory value." (PMID 32478097, 2020).
Hydrocephalus (7 papers, 2018 to 2025). Hydrocephalus is an active distension of the ventricular system of the brain resulting from inadequate passage of CSF from its point of production within the cerebral ventricles to its point of absorption into the systemic circulation. "Some researchers have found through experiments that receptors for AVP (arginine vasopressin) and ANP (atrial natriuretic peptide) in CP are targets for agents to reduce CSF formation, which can be used to treat hydrocephalus." (PMID 35715859, 2022).
ischemia (7 papers, 2009 to 2025). A hypoperfusion of the BLOOD through an organ or tissue caused by a PATHOLOGIC CONSTRICTION or obstruction of its BLOOD VESSELS, or an absence of BLOOD CIRCULATION. "This triggers the release of arginine vasopressin, which has been shown to increase renal oxygen consumption, possibly exacerbating renal injury by causing renal ischaemia and subsequent renal ATP depletion." (PMID 34528132, 2021). "Given the variety of different vasopressin receptors as well as the susceptibility of different tissues to ischemia, it is possible that AVP may have tissue-specific effects." (PMID 29065123, 2017). "Another recently published theory suggests that conditions like eclampsia are related to arginine vasopressin hypersecretion, which in turn can lead to cerebral vasoconstriction, endothelial dysfunction, and ischemia, leading to cytotoxic edema." (PMID 39974296, 2025). "8Br-cGMP (and consequently also NO) inhibits overreactivity of blood vessels to AVP triggered by reperfusion and reduced reaction of arteries for the control and ischemia." (PMID 27563664, 2016). "In contrast, we found AVP significantly decreased LVEF in a model of ischemia reperfusion." (PMID 19549333, 2009). "In addition, the well-known interaction of AVP with the hypothalamic–pituitary–adrenal (HPA) axis during stress further supports the notion that AVP is upregulated in myocardial ischemia owing to an exaggerated neuroendocrine response to ischemia-induced stress." (PMID 40278203, 2025). "As previous studies have noted, AVP may exert cardiac suppressive effects through a variety of mechanisms, therefore, we went on to identify a potential mechanism behind this ischemia-induced cardiac sensitization to vasopressin." (PMID 19549333, 2009).
renal dysfunction (7 papers, 2015 to 2024). "HRS is defined as renal dysfunction due to reduced EABV, or overactivity of vasoactive agents (e.g., AVP)." (PMID 34070416, 2021).
anemia (6 papers, 2014 to 2026). A reduction in the number of red blood cells, the amount of hemoglobin, and/or the volume of packed red blood cells. "While this review has highlighted the potential role of AVP as a contributor to PD complications, it is also possible that AVP upregulation exerts beneficial effects on anemia in PD patients." (PMID 41157262, 2025).
anxiety disorder (6 papers, 2009 to 2025). A category of psychiatric disorders which are characterized by anxious feelings or fear often accompanied by physical symptoms associated with anxiety. "Indeed, in humans, the dysregulation of brain and CSF AVP levels are associated with a number of anxiety disorders." (PMID 30618551, 2018). "As above, dendritic secretion of AVP has been shown to be of central importance in animal models of anxiety disorders, while axonal secretion has been shown to affect fear responses in mice, probably by regulating stress responses through the hypothalamic–pituitary–adrenal axis." (PMID 31779267, 2019). "A hyperactivity of central neuropeptidergic circuits such as CRF and arginine vasopressin (AVP) systems may play a key role in major affective and anxiety disorders." (PMID 23986909, 2013).
breast carcinoma (6 papers, 2017 to 2025). "Altogether, except for the AVP gene, other genes had been reported as candidates for various cancers treatment, including breast cancer." (PMID 38440732, 2024). "The intricate relationship between AVP and oxytocin and their roles in breast cancer patients are emerging areas of increasing research interest." (PMID 37781188, 2023). "Further research is needed to fully understand the relationship between oxytocin and AVP in breast cancer patients and their potential implications for treatment." (PMID 37781188, 2023). "On the other hand, oxytocin system activation can regulate psychological resilience by affecting estrogen and its receptors, the hypothalamic-pituitary-adrenal axis, thyroid function, metabolic levels of 5-HT, and the release of AVP in breast cancer patients." (PMID 37781188, 2023). "Moreover, in arginine vasopressin (AVP) stimulated breast cancer cells, we observed that Barbadin induced apoptosis, autophagy, and cell cycle arrest in the G0/G1 phase, indicating Barbadin’s side-talk with cell death-related targets." (PMID 37243127, 2023). "Breast cancer cells may also aberrantly express AVP, affecting cardiovascular function and emotional behavior." (PMID 37781188, 2023). "Therefore, the abnormal release of AVP from these breast cancer cells may, in conjunction with oxytocin, participate in the regulation of the cardiovascular system while also affecting the emotional behavior of individuals and playing a role in the regulation of resilience." (PMID 37781188, 2023). "Interestingly, various breast cancer cell lines, including MCF-7 and Skbr3, aberrantly express AVP and its receptor, which may produce anti-apoptotic effects." (PMID 37781188, 2023).
cardiac arrest (6 papers, 2007 to 2025). Cessation of breathing and/or cardiac function. "The use of AVP and its synthetic analog terlipressin has received significant attention in clinical practice, especially in septic shock and cardiac arrest." (PMID 25254206, 2014). "Cardiac arrest patients have both severe hypotension and global hypoxia, both of which may stimulate the release of AVP." (PMID 25886856, 2015).
craniopharyngioma (6 papers, 2012 to 2023). A benign, partly cystic, epithelial tumor of the sellar region, presumably derived from Rathke pouch epithelium. "In addition strong immunoreactivity for arginine vasopressin was reported in one very rare sinonasal teratocarcinosarcoma (mixed olfactory neuroblastoma-craniopharyngioma) in a 59-yo man." (PMID 22956963, 2012).
hypercortisolemia (6 papers, 2015 to 2025). "Excessive functionality of the hypothalamic-pituitary-adrenal axis (HPAa) and corticotropin-releasing hormone (CRH) and/or arginine vasopressin (AVP) pathways causes secondary hypercortisolism causes pseudo-Cushing's symptoms." (PMID 41024930, 2025). "Surprisingly, abnormal plasma cortisol responses to AVP have been observed in patients with BMAH-associated hypercortisolism." (PMID 25941513, 2015). "Dehydration can alter memory function due to hypercortisolemia, increased plasma arginine vasopressin concentration, and altered osmotic equilibrium across the blood-brain barrier (BBB) by increasing BBB permeability." (PMID 39650906, 2024). "Involvement of AVP and V1a receptors in hypercortisolism has been confirmed in a patient with an AVP-sensitive BMAH in whom oral administration of a non-peptidic V1a antagonist significantly decreased urinary cortisol level." (PMID 25941513, 2015).
Hypocortisolism (6 papers, 2018 to 2024). "Hypocortisolism also results in renal sodium loss and volume depletion, which are potent stimulators for appropriately increasing the release of AVP." (PMID 36518913, 2022). "This is particularly essential in adrenocortical insufficiency, during which the nonosmotic stimulation of AVP release is elevated because of body fluid depletion and the lack of inhibition of AVP release by glucocorticoids [273•, 321•]." (PMID 29556787, 2018).
orthostatic hypotension (6 papers, 2015 to 2025). Sudden fall of the blood pressure of at least 20/10 mm Hg when a person stands up. "Moreover, we have shown that some cardiovascular biomarkers, such as copeptin (CT-pro-AVP), pro-atrial-natriuretic-peptide (MR-pro-ANP), and pro-adrenomedullin (MR-pro-ADM) may be altered in conditions related to unexplained falls and syncope such as orthostatic hypotension." (PMID 30216373, 2018).
Parkinson disease (6 papers, 2011 to 2025). A progressive degenerative disorder of the central nervous system characterized by loss of dopamine producing neurons in the substantia nigra and the presence of Lewy bodies in the substantia nigra and locus coeruleus. "In this study, we identified seven hub genes—PI3, TMSB15A, CLEC4M, CD4, SEMA6A, PLXND1, and AVP—that collectively drive Parkinson’s disease progression through synergistic mechanisms." (PMID 41329689, 2025).
polycystic kidney disease (6 papers, 2012 to 2021). A usually autosomal dominant and less frequently autosomal recessive genetic disorder characterized by the presence of numerous cysts in the kidneys leading to end-stage renal failure. "The anti-diuretic hormone arginine vasopressin is thought to be a detrimental factor in polycystic kidney disease (PKD)." (PMID 30870430, 2019). "Interestingly, we found that a number of the nodes had previously been linked to polycystic kidney disease (TNF, AGT, AVP)." (PMID 23209428, 2012). "Thus, this pathway may constitute a valid alternative for the treatment of conditions characterized by impairments in vasopressin signaling or vasopressin type 2 receptor (AVPR2) expression, such as NDI, polycystic kidney disease (PKD), or the syndrome of inappropriate secretion of AVP (SIADH)." (PMID 30995798, 2019).
autoimmune disease (5 papers, 2013 to 2024). A disorder resulting from loss of function or tissue destruction of an organ or multiple organs, arising from humoral or cellular immune responses of the individual to their own tissue constituents. "LNPEP is an aminopeptidase that regulates hormones (i.e., arginine-vasopressin and oxytocin), and is involved in trimming peptide antigens for cross-presentation to T cells in autoimmune diseases." (PMID 37250650, 2023).
Borderline personality disorder (5 papers, 2016 to 2021). A personality disorder characterized by impulsive behavior and unpredictable, capricious mood. "We also explored social performance and AVP expression (plasma) in participants with borderline personality disorder (BPD) who experienced a high incidence of childhood stress." (PMID 31819033, 2019).
Cerebral ischemia (5 papers, 2020 to 2025). Restriction of arterial blood supply to the brain associated with insufficient oxygenation to support the metabolic requirements of the tissue. "Considered between the first measurable physiological reactions to cerebral ischemia, the subsequent hormonal cascade results in releasing several stress mediators, AVP and copeptin being among them." (PMID 36648972, 2023). "AVP gene and protein expression were reported as elevated within the SON and PVN in an experimental model of cerebral ischemia and reperfusion, suggesting transcription and translation of AVP are increased in acute brain injury." (PMID 36768443, 2023). "Arginine vasopressin (AVP) plays an important pathophysiological role in various forms of brain injury, including cerebral ischemia, intracerebral hemorrhage, and traumatic cortical injury." (PMID 31949182, 2020). "When administering AVP to these patients, CBF or PbtO2 should be monitored to determine whether the rise in CPP also increases brain oxygenation, which could help prevent cerebral ischemia." (PMID 41375820, 2025).
endotoxemia (5 papers, 2006 to 2023). "In endotoxemia, AVP impairment in late phase of endotoxemia is associated with an increase in the synthesis of pro-inflammatory mediators during and the consequent late production of NO by NOS2." (PMID 33430014, 2021). "To explain the mechanism involved in the plasmid-induced attenuation of MAP drop in LPS-stimulated rats, we determined the gene expression of liver IL-6 and TNF-α and plasma concentration of AVP and NO, key mediators in endotoxemia." (PMID 23137350, 2012). "It has been demonstrated that NO may play a role on the regulation of the HPA axis and AVP synthesis in the hypothalamic paraventricular nucleus (PVN) during endotoxemia." (PMID 33430014, 2021). "In the present study, we do not use AVP receptor antagonists as a pharmacological tool; however, we suggest that AVP may have mediated the attenuation of the systemic inflammatory response during endotoxemia by direct action on its receptors expressed in the cells of the immune system." (PMID 33430014, 2021). "Our previous studies showed a marked decrease in vasopressin (AVP) plasma levels and increase in activation of the hypothalamic-pituitary-adrenal (HPA) axis during the late phase of endotoxemia, observed 6 h after lipopolysaccharide (LPS) administration." (PMID 33430014, 2021).
Kidney Cyst (5 papers, 2017 to 2024). Abnormal fluid filled sac within the kidney, either acquired or congenital. "AVP is a critical driver of postnatal kidney cyst growth, and the suppression of its endogenous production is considered a potential therapeutic intervention in PKD." (PMID 30601830, 2019). "Arginine vasopressin (AVP) is the most important postnatal growth factor for kidney cysts in ADPKD." (PMID 39165901, 2024). "It has been hypothesized that maintaining adequate hydration could also reduce kidney cyst growth by attenuating the release of AVP." (PMID 39165901, 2024).
pituitary adenoma (5 papers, 2020 to 2025). "used an automated LMJ system for profiling of arginine vasopressin and ACTH in normal human pituitary gland and pituitary adenomas." (PMID 36704039, 2022). "The results showed that the signature of arginine vasopressin and ACTH in a series of ACTH secreting and non-secreting pituitary adenomas was consistent with the histopathological evaluation." (PMID 36704039, 2022).
Anorexia (4 papers, 2018 to 2021). Lack of desire to eat (loss of appetite). "In this study, we focused on arginine vasopressin (AVP) in the hypothalamus, which is known to be secreted under chronic stressful condition and related to anorexia." (PMID 32650712, 2020). "Although these data do not define a precise role of AVP in anorexia, we hypothesized that AVP-induced nesfatin-1/NucB2 feeding suppression observed in the present study was affected by two distinct pathways." (PMID 34134629, 2021).
asthma (4 papers, 2013 to 2018). "It is likely that during the process of psychological stress, elevated central AVP leads to airway vagal excitation via activation of AVPNs, which subsequently induces or exacerbates asthma as is supposed by literatures." (PMID 28210214, 2017).
cardiac ischemia (4 papers, 2006 to 2025). "An alternative pathophysiological mechanism that could justify the upregulation of AVP in myocardial ischemia may be related to the fact that AVP has been implicated in the processing of pain sensation and transmission." (PMID 40278203, 2025). "However, a major criticism against earlier in vivo studies has been that the use of unphysiologically high doses of AVP may cause myocardial ischemia by coronary vasoconstriction." (PMID 18291025, 2008). "Arginine vasopressin is activated excessively to maintain adequate systemic perfusion, which is affected by both low cardiac output and myocardial ischemia due to coronary artery involvement by TAAD." (PMID 38310273, 2024). "The main observations in this study were that AVP, at therapeutic levels, reduces cardiac output, carotid-, renal- and myocardial blood flow by increased vascular resistance after experimental acute cardiac ischemia." (PMID 18291025, 2008). "In this regard, AVP upregulation in myocardial ischemia may represent an intricate mechanism that results in the fine-tuning of the coronary vascular tone by exploiting both the vasoconstrictive and vasodilatory effects of AVP." (PMID 40278203, 2025). "No acute side effects were seen (for example, digital and splanchnic hypoperfusion, abdominal distension, bloody stools, necrotizing enterocolitis), or myocardial ischemia, or worsening of metabolic/lactic acidosis that could be related to AVP administration." (PMID 16677425, 2006). "The exact pathophysiological mechanisms responsible for the release of AVP (or its surrogate copeptin) in patients with myocardial ischemia have not been fully elucidated." (PMID 40278203, 2025).
central hypogonadism (4 papers, 2008 to 2022). "Although antibodies to AVP secreting cells have not been studied in our patient, the persistence of CDI despite improvement of the GH deficiency and hypogonadotropic hypogonadism suggest autoimmune hypophysitis." (PMID 21318063, 2008).